SHOX2 (SHOX homeobox 2)
Description:
May be a growth regulator and have a role in specifying neural systems involved in processing somatosensory information, as well as in face and body structure formation.
Synonyms: OG12X; SHOT; OG12
Tractability: No criterion of Open Targets' tractability assessment is met for any kind of drug.
Gene: Protein-coding gene on chromosome 3 (158,095,905 to 158,106,420, reverse strand). Ensembl gene ENSG00000168779.
Subcellular location: Nucleus
Gene Ontology:
Molecular function: DNA-binding transcription factor activity, RNA polymerase II-specific; sequence-specific double-stranded DNA binding; DNA binding; sequence-specific DNA binding
Biological process: cardiac pacemaker cell differentiation; cardiac right atrium morphogenesis; negative regulation of transcription by RNA polymerase II; nervous system development; regulation of heart rate; regulation of transcription by RNA polymerase II; sinoatrial node cell development; sinoatrial node development; sinoatrial valve development; skeletal system development; muscle tissue morphogenesis; positive regulation of axonogenesis; positive regulation of skeletal muscle fiber development; regulation of branching morphogenesis of a nerve; regulation of DNA-templated transcription
Cellular component: chromatin; nucleus
Genetic constraint (gnomAD): Loss-of-function variants: 11 observed, 23.68 expected, observed/expected ratio (o/e) 0.46, 90% interval 0.29 to 0.77. The synonymous counts are far from expectation, so gnomAD's model fits this gene poorly and the ratio says little. Missense variants: 461 observed, 412.79 expected, observed/expected ratio (o/e) 1.12, 90% interval 1.03 to 1.21. Synonymous variants: 239 observed, 191.59 expected, observed/expected ratio (o/e) 1.25, 90% interval 1.12 to 1.39.
Homologues: Orthologues: chimpanzee SHOX2 (99% identical), macaque SHOX2 (99% identical), pig SHOX2 (99% identical), guinea pig SHOX2 (98% identical), rat Shox2 (98% identical), dog SHOX2 (98% identical), mouse Shox2 (98% identical), tropical clawed frog shox2 (81% identical), zebrafish shox2 (77% identical), rabbit SHOX2 (65% identical). Paralogues in human: SHOX (65% identical), ARX (33% identical), RAX (26% identical), OTP (25% identical), VSX2 (25% identical), ALX4 (24% identical), PAX7 (24% identical), PITX2 (24% identical), UNCX (24% identical), PRRX2 (23% identical), ALX1 (23% identical), PITX1 (23% identical), and 38 more.
Diseases named in the same sentence as SHOX2 in open-access papers:
SHOX2 is named in the same sentence as 99 diseases in open-access papers, as found by Europe PMC text mining. Sharing a sentence is not in itself a finding about the gene and the disease. The quoted sentences say what the papers report.
lung carcinoma (67 papers, 2010 to 2026). "Methylation of the SHOX2 gene has been associated with early stages of lung cancer, providing a crucial tool for early diagnosis." (PMID 40191732, 2025). "Collectively, this study reveals that the methylation of 7 genes (TAC1, CDO1, HOXA9, ZFP42, SOX17, RASSF1A and SHOX2) has a big significance in the diagnosis of lung cancer and achieved a diagnostic model with high sensitivity and specificity." (PMID 38315228, 2024). "Among a series of methylation abnormal genes associated with lung cancer, short stature homeobox 2 (SHOX2) is the most intensively studied and is an excellent indicator for the early diagnosis of lung cancer." (PMID 37366966, 2023). "A number of studies have demonstrated frequent promoter methylation in lung cancer cells, including short stature homeobox gene two (SHOX2), RAS association domain family 1, isoform A (RASSF1A) and homeobox A9 (HOXA9)." (PMID 36176402, 2022). "High SHOX2 copy number variation in cancer cells leads to elevated levels of extracellular methylated SHOX2 DNA that can be used for diagnostic and prognostic purposes for patients with advanced lung cancer." (PMID 34465361, 2021). "Relevant pieces of evidence show that the promoter hypermethylation of the short stature homeobox gene two (SHOX2) has been identified as diagnostic biomarkers for lung cancer." (PMID 33425721, 2020). "In parallel, we developed a ddPCR assay for SHOX2, a validated epigenetic diagnostic biomarker for lung cancer." (PMID 31817025, 2019). "Further well-designed (multi-center) and prospective large-scale studies are required to validate the diagnostic value of gene methylation, especially for the SHOX2 gene in bronchial aspirates of lung cancer." (PMID 28977861, 2017). "Contrarily, gain of SHOX2 methylation in tumor tissues has been shown to be associated with good prognosis in lung cancer patients." (PMID 25229548, 2014). "Aberrant DNA methylation of SHOX2 is a hallmark of lung cancer tumors and correlates to an amplification of the respective locus 3q25.3." (PMID 24386354, 2013). "The objective of this study was to show that SHOX2 DNA methylation is a useful tumor marker to aid the diagnostic workup for suspected lung cancer." (PMID 21047392, 2010). "When lung cancer patients have bronchial aspirates, the Epi pro-Lung BL Reflex Assay is a powerful and practical diagnostic technique for detecting elevated DNA methylation of the SHOX2 gene locus." (PMID 36552956, 2022). "Hence, we further analyzed the diagnostic capacity of the P16, RASSF1A, APC and SHOX2 methylation based on the use of bronchial aspirates in lung cancer." (PMID 28977861, 2017). "Hypermethylation of SHOX2 is frequently observed in lung cancer tissues and can be detected in body fluids such as blood and sputum." (PMID 40191732, 2025). "Several studies have demonstrated the high sensitivity and specificity of SHOX2 methylation for lung cancer diagnosis." (PMID 40191732, 2025). "SHOX2 methylation has been known to have both high sensitivity and specificity for lung cancer detection, while RASSF1A methylation provides additional diagnostic accuracy when used in combination." (PMID 40191732, 2025). "SHOX2: The methylation status of SHOX2 gene is a well-established biomarker for lung cancer detection." (PMID 40191732, 2025). "Greatly, a diagnostic kit that targets SHOX2 and PTGER4 using MethyLight technology has received FDA approval, offering a novel method for the early detection of lung cancer." (PMID 40666096, 2025). "For instance, the DNA methylation status of SHOX2/PTGER4 in plasma were proved to be valuable biomarkers for diagnosing lung cancer, and had been practically applied in clinical settings." (PMID 41341575, 2025). "The effective early-stage diagnosis of single SHOX2 promoter methylation remains challenging when compared to advanced lung cancer." (PMID 40666096, 2025).
lung carcinoma (continued). "These methods can identify tissue-specific methylation patterns that are highly enriched in cancer, such as those in SEPT9 (colorectal cancer), SHOX2 (lung cancer), and GSTP1 (prostate cancer)." (PMID 41020861, 2025). "Numerous studies have indicated the significance of SHOX2 across various cancer types, including lung cancer, Matt." (PMID 40515636, 2025). "For instance, methylation of genes such as SHOX2 and RASSF1A in plasma has been associated with lung cancer in its early stages, demonstrating the potential of blood-based assays for non-invasive screening." (PMID 40191732, 2025). "The diagnostic sensitivity of SHOX2 and RASSF1A was higher in central lung cancer compared to peripheral lung cancer (P < 0.01)." (PMID 38429660, 2024). "Various studies have devised methylation biomarkers for diverse cancers like lung, colorectal, cervical, and bladder cancers, which find application in clinical diagnosis, such as the three-gene methylation biomarker (SHOX2/RASSF1A/PTGER4) for lung cancer." (PMID 38680421, 2024). "To this end, we compared the DNA methylation status of 7 genes including TAC1, CDO1, HOXA9, ZFP42, SOX17, RASSF1A and SHOX2 in lung cancer cases with different stages." (PMID 38315228, 2024). "The combined promoter methylation assay for lung cancer using SHOX2 and RASSF1A demonstrated a sensitivity of 89.8% and a specificity of 90.4% in FFPE specimens." (PMID 38840077, 2024). "Here, we explored the significance of the DNA methylation of 7 genes including TAC1, CDO1, HOXA9, ZFP42, SOX17, RASSF1A and SHOX2 in the blood cfDNA samples in distinguishing lung cancer from benign nodules and healthy individuals." (PMID 38315228, 2024). "Then, we explored the diagnosis value of the DNA methylation status of 7 genes including TAC1, CDO1, HOXA9, ZFP42, SOX17, RASSF1A and SHOX2 in lung cancer." (PMID 38315228, 2024). "SHOX2 hypermethylation has been noticed in the bronchial aspirates, pleural effusions, and blood plasma of patients with lung cancer." (PMID 39132504, 2024). "Compared to RASSF1A, the positive rate of SHOX2 methylation was higher across all lung cancer pathological subgroups." (PMID 38429660, 2024). "While SHOX2 and RASSF1A serve as promising cancer biomarkers and exhibit commendable diagnostic capabilities for detecting lung cancer in alveolar lavage fluid, they cannot discern the pathological subtypes." (PMID 38429660, 2024). "Consistent with previous studies, SHOX2 proved to be a highly sensitive indicator for the diagnosis of lung cancer, with higher levels of methylation observed in patients with SCLC (95.7%) and LUSC (92.5%) compared to patients with LUAC (67.3%)." (PMID 38429660, 2024). "They found that DNA methylation of SHOX2 is a highly sensitive and specific biomarker for analyzing lung cancer patients." (PMID 38982390, 2024). "The results of another study to measure DNA methylation of SHOX2 in lung cancer with HeavyMethyl technology indicated that this test is a reliable and powerful tool for lung cancer diagnosis." (PMID 38982390, 2024). "The results showed that the methylation rate of CDO1 and SHOX2 showed significantly different between the I-IV stages of lung cancer." (PMID 38315228, 2024). "Here, we compared the DNA methylation status of 7 genes including TAC1, CDO1, HOXA9, ZFP42, SOX17, RASSF1A and SHOX2 in lung cancer cases with I–IV stages." (PMID 38315228, 2024). "In summary, SHOX2 and RASSF1A exhibited different diagnostic thresholds, and the appropriate ΔCt thresholds effectively differentiated between lung cancer and benign diseases." (PMID 38429660, 2024). "For instance, in lung cancer patients, the methylation of SHOX2/PTGER4/RASSF1A in plasma DNA has been employed as a biological marker for identifying lung cancer and has found practical applications in clinical settings." (PMID 38680421, 2024).
lung carcinoma (continued). "Through a comparative analysis of SHOX2 methylation in lung cancer and normal tissues, it was observed that 96% of tumor tissues exhibited an elevated level of methylation." (PMID 38840077, 2024). "In this study, we explored the significance of the DNA methylation of 7 genes including TAC1, CDO1, HOXA9, ZFP42, SOX17, RASSF1A and SHOX2 in the blood cfDNA samples in distinguishing lung cancer from benign nodules and healthy individuals." (PMID 38315228, 2024). "Regarding lung cancer, an assay designed to quantify methylation of the SHOX2 gene in bronchial aspirates and pleural effusion samples, called Epi proLung®, has been developed." (PMID 37511475, 2023). "A meta-analysis of SHOX2 gene promoter methylation and lung cancer showed that the SHOX2 gene promoter methylation rate increased in lung cancer tissue, suggesting that SHOX2 methylation was significantly related to lung cancer." (PMID 37158875, 2023). "The results showed that high SHOX2 expression levels were significantly correlated with shorter OS in gastric cancer (GC), liver cancer, lung cancer and ovarian cancer (OV) via Kaplan-Meier plotter portal." (PMID 37170390, 2023). "We analyzed the diagnostic sensitivity of SHOX2 and RASSF1A methylation in BFF/BALF in different histological subtypes of lung cancer." (PMID 37182143, 2023). "In clinical practice, many of these DMRs have the potential to predict disease progression, including in patients with stage IV lung cancer (SHOX2, RARB/RASSF1A, RARB, RASSF1A/APC, DCLK1, BRMS1, SOX17, SFN, CHFR, and APC/RASSF1A/CDH13/CDKN2A)." (PMID 36765815, 2023). "The promoter methylation of short stature homeobox gene two (SHOX2) and RAS association domain family 1, isoform A (RASSF1A) have been identified as diagnostic and prognostic biomarkers for lung cancer." (PMID 37182143, 2023). "It should be noted that SHOX2 analysis showed higher specificity for lung cancer when performed in bronchial aspirates than in pleural effusion samples." (PMID 37511475, 2023). "Accumulating evidence suggests that aberrant promoter CpG island hypermethylation of SHOX2 and RASSF1A can serve as a diagnostic and prognostic biomarker for lung cancer, colorectal cancers, biliary tract cancers, and head and neck squamous cell carcinomas." (PMID 36691467, 2023). "The detection of methylation patterns in Short Stature Homeobox 2 (SHOX2) and Ras-association domain family member 1A (RASSF1A) have been preliminarily used for the diagnosis of lung cancer." (PMID 35837113, 2022). "By comparing the methylation of SHOX2 in lung cancer and normal tissues, ninety-six percent (53 out of 55) of matched pairs showed a higher methylation level in tumor tissues." (PMID 35837113, 2022). "We searched MEDLINE, EMBASE, Ovid, Web of Science and CNKI for literatures related to the relationship between SHOX2 gene promoter hypermethylation and lung cancer." (PMID 34275516, 2021). "It has been demonstrated that the SHOX2 locus is frequently amplified and hypermethylated in lung cancers." (PMID 34465361, 2021). "The purpose of the present work was to quantitatively evaluate the diagnostic value of abnormal hypermethylation in short state homeobox 2 (SHOX2) promoter region in lung cancer by evidence-based medicine." (PMID 34275516, 2021). "The promoter methylation of SHOX2 has been identified as a valuable biomarker for lung cancer diagnosis in several research studies." (PMID 34408226, 2021). "The methylation analysis of SHOX2, RASSF1A, and PTGER4 panel in plasma showed an efficient diagnostic ability in lung cancer diagnosis." (PMID 34408226, 2021). "As a crucial transcriptional regulator in several genetic disorders, SHOX2 has been demonstrated to be an excellent biomarker in the diagnosis and evaluation of many types of cancers, including lung cancer." (PMID 34465361, 2021).
lung carcinoma (continued). "SHOX2 hypermethylation has been reported to occur frequently in a variety of tumors plasma, including lung cancer, head and neck squamous cell carcinoma (HNSCC), renal cell carcinoma (RCC), and colorectal cancer." (PMID 34408226, 2021). "Among them, PTGER4, RASSF1A, and SHOX2 methylation biomarkers showed high potential in the diagnosis and prognosis of lung cancer." (PMID 33691657, 2021). "Prostaglandin E receptor 4 gene (PTGER4), ras association domain family 1A (RASSF1A), and short stature homeobox gene two (SHOX2) methylation have been separately identified as valuable biomarkers for lung cancer diagnosis in several research studies." (PMID 33691657, 2021). "The Epi proLung assay can be used to detect lung cancer by the determination of the methylation status of the short stature homeobox 2 (SHOX2) and the prostaglandin E receptor 4 (PTGER4) gene." (PMID 33918147, 2021). "The performance of SHOX2/PTGER4 biomarkers to detect lung cancer in plasma samples was initially tested in the study that included 118 lung cancer patients, covering all major histological types and a broad range of stages and 212 healthy controls." (PMID 32631437, 2020). "The combination of single biomarkers with high stage-specificity and histological type specificity (SHOX2 and PTGER4 DNA methylation and IDH1) showed better diagnostic performance in the detection of lung cancers compared with single marker assessment." (PMID 31888670, 2019). "SHOX2 methylation, as determined from bronchial aspirates, has demonstrated good sensitivity and a high specificity as a biomarker for lung cancer." (PMID 31316555, 2019). "In 2011, SHOX2 methylation was assessed in circulating cell-free DNA obtained from blood plasma and showed a sensitivity of 60% and a specificity of 90% for lung cancer diagnosis in a case-control study with 343 subjects." (PMID 31316555, 2019). "Although, the discriminative ability in detection of lung cancers of the SHOX2/PTGER4 DNA methylation marker panel has been confirmed." (PMID 31888670, 2019). "Commercially available Epi proLung detects promoter methylation of short stature homeobox 2 (SHOX2) in bronchial lavage of lung cancer patients with a sensitivity of 78% and specificity of 96%." (PMID 29614786, 2018). "The SHOX2 gene had a notably higher methylation rate in bronchial aspirates of patients with lung cancer than in cancer-free controls." (PMID 28977861, 2017). "Second, based on small sample sizes, the results regarding the comparison of the different tumor histotypes should be done to further validate the detection of the SHOX2 gene in lung cancer histology in the future." (PMID 28977861, 2017). "In conclusion, our findings suggest that the SHOX2, P16, RASSF1A and APC methylation was associated with lung cancer in bronchial aspirates." (PMID 28977861, 2017). "Of these genes, four genes with more than three studies evaluated the relationship between the methylation status of the P16, RASSF1A, APC and SHOX2 genes and lung cancer." (PMID 28977861, 2017). "Aberrant DNA methylation of SHOX2 has been extensively characterized as a biomarker for the diagnosis of lung cancer." (PMID 27999621, 2016). "One biomarker under development is methylated SHOX2, which has shown promise in blood-based diagnosis of lung cancer, and has more recently been investigated as marker of early response to treatment in lung cancer patients." (PMID 26764421, 2016). "DNA from lung cancer specimens appeared to be significantly higher methylated at the SHOX2 gene locus as compared to morphologically normal adjacent tissue, and a correlation of hypermethylation and gene amplification has been described." (PMID 27999621, 2016). "PMR values >100% have been previously reported for SHOX2 in lung cancer, when ACTB was used as a reference, and were attributed to amplification of the SHOX2 locus or deletion of the ACTB locus." (PMID 27999621, 2016).